RNU6-598P (RNA, U6 small nuclear 598, pseudogene)
Gene: Small nuclear RNA gene on chromosome 10 (30,299,569 to 30,299,673, reverse strand). Ensembl gene ENSG00000200887.
Homologues: Orthologues: chimpanzee U6 (100% identical), macaque U6 (97% identical), guinea pig U6 (80% identical), rat LOC120100172 (75% identical). Paralogues in human: RNU6-116P (91% identical), RNU6-1060P (90% identical), RNU6-10P (90% identical), RNU6-1175P (90% identical), RNU6-33P (90% identical), RNU6-698P (90% identical), RNU6-1 (89% identical), RNU6-11P (89% identical), RNU6-15P (89% identical), RNU6-19P (89% identical), RNU6-2 (89% identical), RNU6-25P (89% identical), and 1286 more.